SPRR1A (small proline rich protein 1A)
Diseases named in the same sentence as SPRR1A in open-access papers (continued):
Sharing a sentence is not in itself a finding about the gene and the disease.
tumor (8 papers, 2018 to 2025). "In the univariate analysis, significant risk factors were residual tumor status of R1 (HR 2.498, 95% CI 1.414 to 4.415, p = 0.00163) and high SPRR1A expression (HR 1.716, 95% CI 1.031 to 2.856, p = 0.0378)." (PMID 35617311, 2022). "Furthermore, we found in tumour and margin samples from patients with concomitant diseases an association between SPRR1A and SPRR2A levels." (PMID 40647632, 2025). "We suggest that SPRR1A may be associated with tumour transformation." (PMID 40647632, 2025). "There was a difference in the concentration of the SPRR1A protein in the G2 group between the tumour and margin samples, with a higher level of protein in the tumour (2.092 (1.643–5.316) vs 1.103 (0.370–1.409); p = 0.0452)." (PMID 40647632, 2025). "To date, few studies have focused on SPRR1A expression in the tumour margin in the context of nodal status." (PMID 40647632, 2025). "In contrast, in another study involving 127 OSCC samples and healthy tissue from adjacent oral areas, the authors found that reduced expression of both SPRR1A and SPRR2A in tumour tissues was associated with the occurrence of lymphatic metastasis." (PMID 40647632, 2025). "The Top 3 genes that were upregulated upon tumor growth were found to be Sprr1a (small proline-rich protein 1A, FC = 19.09, p < 0.01), Gal (Galanin, FC = 5.11, p < 0.0001) and FGF23 (fibroblast growth factor receptor 23, FC = 4.22, p < 0.001)." (PMID 37573456, 2023). "A multivariate analysis indicated that a high SPRR1A expression (HR 1.706, 95% CI 1.018 to 2.862, p = 0.0427) and residual tumor status (HR 2.687, 95% CI 1.487 to 4.855, p = 0.00106) were independent prognostic factors." (PMID 35617311, 2022). "In addition, monitoring SPRR1A levels in the margin could be a useful tool in assessing the risk of micrometastasis or early premalignant lesions, which would allow a more precise mapping of the extent of the tumour lesion when planning surgical circumstances and delineating resection boundaries." (PMID 40647632, 2025). "Additionally, we found elevated levels of SPRR1A protein levels in tumour samples, compared to margin samples, in patients with G2 status." (PMID 40647632, 2025). "After adjusting tumor purity, the expression of ALOX12B was negatively associated with IGFR1, AKT1, MTOR, and EIF4EBP1, and the same correlation could also be observed in SPRR1A." (PMID 35768785, 2022). "From a prognostic perspective, the combination of measurements of SPRR1A levels in the margin (as a marker of early “field cancerization” changes) and in the tumour may allow better differentiation of patients in terms of the risk of progression and metastasis." (PMID 40647632, 2025). "Our aim was to determine the concentration of SPRR1A and SPRR2A in tumours samples obtained from 61 patients with HNSCC (OSCC, OPSCC, LSCC, HPSCC, NCSCC, and SSCC)." (PMID 40647632, 2025). "Due to the significant influence of the pathological stage and residual tumor status on the patient prognosis, we excluded stage III and R1 cases, respectively, and assessed the prognostic value of the SPRR1A expression again." (PMID 35617311, 2022). "Also, we found a statistically significant difference between the SPRR1A and SPRR2A levels in tumour and margin samples obtained from patients that either abstain and occasionally or regularly consume alcohol." (PMID 40647632, 2025). "We speculate that the levels of SPRR1A and SPRR2A proteins in tumour samples will be significantly correlated with the following factors, such as selected demographic factors, smoking habit, alcohol consumption, and p16/HPV status." (PMID 40647632, 2025). "Interestingly, although OS is a tumor of mesenchymal origin, upregulated genes in MG-OKS cells included epithelial-related genes, such as small proline-rich protein 2A (SPRR2A), SPRR1A, keratin 6A (KRT6A), and keratin 6B (KRT6B)." (PMID 33008481, 2020).
tumor (continued). "Therefore, the expression of the studied SPRR1A and SPRR2A in the margin tissue may differ from their levels in healthy tissue, which may lead to under- or overestimation of the expression differences between the tumour and the margin." (PMID 40647632, 2025). "Therefore, the results of comparing SPRR1A and SPRR2A levels between tumour and margin samples may not fully reflect the true picture of molecular changes associated with tumour transformation." (PMID 40647632, 2025).
cardiac disease (2 papers, 2021 to 2023). "Given that upregulation of SPRR1A or downregulation of miR-150 also underlies other forms of cardiac disease, the deleterious action of SPRR1A and the protective action of miR-150 in whole mouse hearts and HCFs are likely applicable to multiple stress settings." (PMID 37468478, 2023). "Ankrd1 is a marker of immature CM observed during embryonic development, and also of cardiac diseases, while Sprr1a is correlated with cardioprotection in ischemic injury." (PMID 35050211, 2021).
adenocarcinoma (1 paper, 2022). A common cancer characterized by the presence of malignant glandular cells. "Squamous differentiation, unlike the adenocarcinoma component, essentially expresses SPRR1A." (PMID 35617311, 2022).
bacterial infection (1 paper, 2012). "For instance, Ppbp could be regulating kidney development, inflammation, and defense against bacterial infection; Sprr1a is another gene highly dependent on tRA/RAR signaling in mediating tissue repair and regeneration relevant to kidney injury." (PMID 23049847, 2012).
infection (1 paper, 2022). The state of being infected such as from the introduction of a foreign agent such as serum, vaccine, antigenic substance or organism. "To test the Sprr1a−/−;Sprr2a−/− mice for susceptibility to infection, we inoculated the skin of wild-type and Sprr1a−/−;Sprr2a−/− mice with 1 × 106 CFU of a bioluminescent strain of MRSA by topical application." (PMID 35234613, 2022).
SPRR1A also shares sentences with these, for which no sentence is quoted: metastatic melanoma (4 papers); squamous cell carcinoma (3); cervical cancer (2); basal cell carcinoma (1); breast invasive carcinoma (1); cardiovascular diseases (1); childhood onset asthma (1); endocrine diseases (1); gastric cancer (1); gastrointestinal disease (1); head and neck squamous cell carcinoma (1); heart failure (1); keratoconus (1); kidney diseases (1); kidney stone (1); pancreatic ductal adenocarcinoma (1); pancreatitis (1); periodontitis (1); prostate carcinoma (1); psoriasis (1); uveal melanoma (1).